MDM2 (MDM2 proto-oncogene)
Diseases named in the same sentence as MDM2 in open-access papers (continued):
Sharing a sentence is not in itself a finding about the gene and the disease.
retinoblastoma (continued). "Interestingly, this type of mitochondrial morphology is observed in retinoblastoma (described in the next section), which leads to the hypothesis that a large fraction of MDM2 could localize to the mitochondria and induce changes in its morphology and functions." (PMID 36338723, 2022). "Transcriptome analysis of RB1 knockout organoids and primary retinoblastoma revealed gain of a retinoblastoma expression signature in the organoids, characterized by upregulation of RBL1 (p107), MDM2, DEK, SYK and HELLS." (PMID 35565295, 2022). "In studies establishing that MDM2 regulates MYCN in retinoblastoma, we noticed that retinoblastoma cell line RB176 expressed MYC in addition to MYCN." (PMID 33425720, 2020). "The regulatory specificity was best illustrated in retinoblastoma cell line RB176, in which MYCN and MYC are co-expressed yet MDM2 was needed to sustain only MYCN." (PMID 33425720, 2020). "While the affinity of the MDM2 antibody used in this study was much lower than the MDM4 antibody, there was still significantly more MDM4 protein in retinoblastoma xenografts than MDM2 (>50 fold)." (PMID 22916154, 2012). "In a series of orthotopic xenografts of human retinoblastoma from our lab and Memorial Sloan Kettering Cancer Center (MSKCC), MDM4 protein was expressed at high levels and MDM2 was below the limit of detection." (PMID 22916154, 2012). "To test if there was any correlation between the SNP genotypes and MDM2 and MDM4 gene expression in retinoblastoma, we performed gene expression arrays on 22 of the 44 primary retinoblastoma tumors using the U133av_2 affymetrix chip." (PMID 22916154, 2012). "In this study, we analyzed the MDM2 and MDM4 mRNA and protein expression in human fetal retinae and human retinoblastoma." (PMID 22916154, 2012). "The present study investigates the use of nutlin-3a as a proof of concept for the use of MDM2 inhibitors as non-genotoxic approaches for retinoblastoma." (PMID 41282624, 2025). "Data from Retinoblastoma and Myelodysplastic syndromes (MDS) implicate MDM2 in pseudohypoxia." (PMID 38352889, 2024). "Similar to MDM2, MDMX is often found to be upregulated in retinoblastoma." (PMID 37667345, 2023). "Moreover, ALRN-6924, a stabilized, cell-permeating peptide that inhibits both MDM2 and MDMX, is under investigation (NCT03654716) for use in retinoblastoma." (PMID 37509256, 2023). "New classes of small molecule MDM2/MDM4 inhibitors are being evaluated in Phase I/II studies in combination with broad-spectrum and targeted therapies; one of these is a trial in pediatric cancer including retinoblastoma." (PMID 35433448, 2022). "Nonetheless, MDM2 and MDM4 are both expressed in all Rb cone clusters, likely impeding an ARF-mediated response and further promoting cone proliferation and survival in Rb tumors." (PMID 34003213, 2021).
retinoblastoma (continued). "In spite of its significantly lower affinity toward MDM4 than toward MDM2, the near absence of MDM2 in a retinoblastoma model with elevated MDM4, resulted in remarkable response when the drug was administered directly to the tumor site." (PMID 30689920, 2019). "Copy number alterations are rare in retinoblastoma and MDM2 has not been analyzed for a relationship between genetic gain and gene or protein expression in retinoblastoma." (PMID 22916154, 2012). "Collectively, these data showed MDM2 and HIF-1α are of great importance in the generation of CSCs in RB and inhibition of these 2 proteins could significantly decrease the stem-cell properties of primary retinoblastoma cells." (PMID 36741966, 2023). "Moreover, it has been observed that, in order to escape apoptosis and further proliferate, retinoblastoma cell proliferation depends on the expression of proteins including RXRγ, MYCN, MDM2, and TRβ2, which are also greatly produced by retinal cone progenitor cells." (PMID 34195690, 2021). "While the comparison of MDM2 and MDM4 protein levels across cell lines clearly shows that the relative abundance of the proteins is different, it is impossible to directly compare the absolute levels of MDM2 and MDM4 in retinoblastoma samples because the antibodies may have different affinities." (PMID 22916154, 2012).
lung adenocarcinoma (42 papers, 2013 to 2025). A carcinoma that arises from the lung and is characterized by the presence of malignant glandular epithelial cells. "Another study in 292 lung adenocarcinoma patients show opposite results that MDM2 rs2279744 was associated with an increased risk of grade 3-4 hematologic toxicity in recessive model (OR = 2.128; 95% CI: 1.198–3.777; p = 0.010)." (PMID 39234108, 2024). "Invasive subtypes of lung adenocarcinoma (LUAD) show MDM2 amplification that is associated with poor survival." (PMID 35158979, 2022). "It has been discovered that lung adenocarcinoma patients with MDM2 amplification and protein overexpression have a poor prognosis." (PMID 39590120, 2024). "MDM2 is significantly highly expressed in lung adenocarcinoma tissues compared with adjacent tissues, and is regarded as a proto-oncogene." (PMID 38547196, 2024). "Lung adenocarcinoma pathology and biology is heterogeneous, which is reflected by tumor MDM2 amplification status." (PMID 35158979, 2022). "Lung adenocarcinoma patients with MDM2 amplification displayed poor survival as compared to those with normal MDM2 CN." (PMID 35158979, 2022). "In our study, bioinformatics analysis found that MDM2 was up‐regulated in lung adenocarcinoma and lung squamous cell carcinoma cells compared with normal tissue, and the elevated level of MDM2 was associated markedly with short survival in NSCLC patients." (PMID 35692096, 2022). "MDM2 has been documented to activate the Smad2 /3 signaling pathway to promote the EMT of lung adenocarcinoma cells." (PMID 32423468, 2020). "In the increase in CDK4 copy number that occurred in five lung adenocarcinomas, four of these exhibited an increase in MDM2 copy number." (PMID 32711494, 2020). "We also identify a new binding partner of Mdm2, HMCS1_HUMAN, in lung adenocarcinoma cells." (PMID 40559991, 2025). "MDM2 is significantly upregulated in lung adenocarcinoma tissues compared with adjacent tissues." (PMID 33612481, 2021). "In addition, an increase in MDM2 copy number was also detected from another lung adenocarcinoma patient." (PMID 32711494, 2020).
lung adenocarcinoma (continued). "Moreover, our study found that silencing of DANCR reduced the protein levels of Smad2/3, which might be regulated by MDM2, since MDM2 has been documented to promote Smad2/3 activation in lung adenocarcinoma." (PMID 32423468, 2020). "We investigated the role of MDM2 status on response to MDM2 inhibitor RG7112 on migratory and invasive ability of lung adenocarcinoma cells using in vitro transwell migration and invasion assays." (PMID 35158979, 2022). "The most significantly focally amplified genes in lung adenocarcinomas are NKX2-1, MYC, TERT, MCL1 and MDM2, while in LSQCC the most amplified were SOX2, CCND1, FGFR1, MYC, YES1, MIR205 and EGFR." (PMID 30060526, 2018). "Another study found the MDM2 protein-positive expression rate was 57.8% (26/45) in lung adenocarcinoma tissues, and negative expression was found in normal tissue adjacent to tumor (P <0.01)." (PMID 33968713, 2021).
liver cancer (39 papers, 2011 to 2026). An epithelial or non-epithelial malignant neoplasm that arises from the liver. "Clinically, aberrant upregulation of MDM2 is associated with drug resistance, metastasis, and poor prognosis in liver cancer." (PMID 36038536, 2022). "Using the Kaplan–Meier Plotter database (MDM2 DFS: Hazard ratio [HR] = 2.1, P = 0.0018; MDMX DFS: HR = 1.8, P = 0.012), multivariable analysis for Disease Free Survival (DFS) determined that high MDM2 or MDMX expression is associated with shorter DFS in liver cancer patients." (PMID 37963859, 2023). "Another alkaloid, matrine, has been reported to inhibit MDM2 expression by reducing MDM2 mRNA synthesis in liver cancer cells." (PMID 39764218, 2024). "We found that HERPUD1 reduces MDM2 ubiquitination in liver cancer cells, while MDM2 induces the ubiquitination of GSS, thereby reducing the content of GSS, and finally inhibiting the synthesis of GSH to increase ferroptosis." (PMID 36038536, 2022). "Compared with normal liver cancer cells, the ubiquitination of MDM2 was increased in HERPUD1-sg1 liver cancer cells by co-IP experiments, and the half-life of MDM2 was prolonged in liver cancer cells knocked out HERPUD1 by CHX chase experiments." (PMID 36038536, 2022). "The polyclonal anti-MDM2 antibody was used as primary antibody to detect the expression of MDM2 in liver cancer and normal hepatic tissues." (PMID 24955377, 2014). "In the current study, the expression profile of MDM2 in liver cancer tissues and normal liver tissues was examined by immunohistochemistry with tissue array slides." (PMID 24955377, 2014). "Likewise, VHL ligand requires to be accommodated in the PROTAC template to target the MDM2 E3 ligase that is overexpressed in liver cancer." (PMID 33840388, 2021).
liver cancer (continued). "Among the liver cancer cells, SMMC7721 cells expressed the highest levels of mdm2." (PMID 30176896, 2018).